SLC22A17 (solute carrier family 22 member 17)
Diseases named in the same sentence as SLC22A17 in open-access papers (continued):
Sharing a sentence is not in itself a finding about the gene and the disease.
tumor (continued). "There was a significant difference (P < 0.05) in tumor mutational burden between patients in the high and low group, high expression of SUPV3L1 and infiltration of Th2 cells and T helper cells and low expression of SLC22A17 and infiltration of Mast cells coupled with a high mutational burden." (PMID 32164594, 2020). "Brain metastatic tumor cells secrete LCN2, which binds to SLC22A17 on astrocytes, activating JAK2/STAT3 signaling and inducing astrocyte activation and chemokine secretion, thereby facilitating macrophage recruitment." (PMID 41436606, 2025). "On this basis, we conducted an in silico study to evaluate the role of LCN2, SLC22A17, and MMP9 genes and related isoforms in different tumor types by following specific workflow steps." (PMID 36211450, 2022). "In this context, the LCN2–SLC22A17–MMP9 (lipocalin 2—solute carrier family 22 member 17—matrix metallopeptidase 9) pathway contributes to the establishment and remodeling of TME, which is responsible for the tumor progression." (PMID 36211450, 2022). "Survival analysis was performed using Xena UCSC, retrieving the log-rank test values and p-values calculated for the CG probesets related to LCN2, SLC22A17, and MMP9 in each tumor type." (PMID 36211450, 2022). "Among the SLC22A17 isoforms, the coding isoforms ENST00000354772.7 and ENST00000206544.8 showed the highest expression levels in both tumor and normal samples." (PMID 36211450, 2022). "On these bases, the role of LCN2, SLC22A17, and MMP9 was evaluated in different tumor types performing in silico analysis using the expression and methylation data available on TCGA and GTEx datasets." (PMID 36211450, 2022). "The correlation analysis was also carried out between the methylation levels and expression of LCN2, SLC22A17, and MMP9 in each tumor type." (PMID 36211450, 2022). "This analysis allowed us to identify the median levels of LCN2, SLC22A17, and MMP9 genes and isoforms of each tumor type that were upper to 3rd or lower to 1st quartiles of corresponding normal tissue." (PMID 36211450, 2022). "For the correlation between SLC22A17, APOD, and tumor drug resistance, we next determined the effect of SLC22A17 and APOD on drug sensitivity." (PMID 34306002, 2021). "Additionally, LCN2 binds to its receptor SLC22A17 on tumor cells, activating the JAK2–STAT3 signaling pathway, which elevates VEGF-A expression and secretion, thereby promoting tumor neovascularization." (PMID 41436606, 2025). "Moreover, the impact of expression and methylation status of LCN2, SLC22A17, and MMP9 on overall survival and progression free interval was tumor type–dependent." (PMID 36211450, 2022). "This study provides an overview on the epigenetic regulation of LCN2, SLC22A17, and MMP9 in the major tumor types allowing the identification of novel DNA methylation biomarkers and potential epi-drug targets of TME involved in tumor progression and drug resistance." (PMID 36211450, 2022). "Unlike LCN2, SLC22A17 was predominantly downregulated in more than 75% of tumor types, showing statistical significance (FC ≥ 1.4 or ≤ −1.4; p ≤ 0.05) for the gene and seven of its isoforms." (PMID 36211450, 2022). "Despite the role of NGAL and MMP9 in tumor invasion and metastasis has been deeply investigated, the exact involvement of SLC22A17 in cancer development has not been yet clarified." (PMID 36211450, 2022). "The role in tumorigenesis of LCN2, SLC22A17, and MMP9 genes and their gene isoforms as key players of TME interaction was assessed by performing differential transcriptomic analysis of these targets between TCGA tumor samples and GTEx normal tissues." (PMID 36211450, 2022). "Unlike what has been observed for LCN2 and MMP9, the SLC22A17 expression was downregulated in most tumor types (66.7%) compared to normal tissue samples." (PMID 36211450, 2022).
tumor (continued). "Finally, the correlation analysis between genes and isoforms of LCN2, SLC22A17, and MMP9 in both normal and tumor samples was performed to detect any interaction between the three genes, including the relative isoforms." (PMID 36211450, 2022). "The correlation analysis performed on all TCGA tumor types highlighted a negative correlation between LCN2 and SLC22A17 expression." (PMID 36211450, 2022).
cancer (12 papers, 2018 to 2025). A tumor composed of atypical neoplastic, often pleomorphic cells that invade other tissues. "For instance, the decrease of SLC22A17 inhibits iron efflux from cancer cells resulting in iron-dependent proliferation and resistance to apoptosis." (PMID 36211450, 2022). "In contrast, the SLC22A17 and APOD genes were negatively associated with RNAss and DNAss in most cancers." (PMID 34306002, 2021). "We observed that APOD was dysregulated in 17 types of cancers and that SLC22A17 was dysregulated in 16 types of cancers, with significant p-values." (PMID 34306002, 2021). "In almost all cancers, SLC22A17 and APOD have positive relationships with the StromalScore, ImmuneScore and ESTIMATEScore." (PMID 34306002, 2021). "In addition, cancer cells used LCN2/SLC22A17 to accumulate extracellular iron in the CSF and thus outcompete other cells in the leptomeninges." (PMID 41303420, 2025). "On the other hand, the intracellular iron overload induced by SLC22A17 downregulation could have detrimental effects on cancer cell survival increasing oxidative stress and activating ferroptosis during pharmacological treatment." (PMID 36211450, 2022). "Based on this evidence, the blockage of SLC22A17 could sensitize the cancer cells to iron-dependent death." (PMID 36211450, 2022). "Not surprisingly, we found that APOD and SLC22A17 have a wide range of stromal scores in association with 33 different cancer types." (PMID 34306002, 2021). "Hence, we detected the expression of SLC22A17 and APOD in 33 types of cancers and determined the association of the two genes with cancer stemness-related indicators." (PMID 34306002, 2021). "Interestingly, we observed that the APOD and SLC22A17 genes were negatively correlated with RNAss and DNAss in almost all of the cancer types." (PMID 34306002, 2021). "Then, we analyzed the expression levels of APOD and SLC22A17 in 33 types of cancers." (PMID 34306002, 2021). "However, no relevant mutations or Single Nucleotide Polymorphisms (SNPs) affecting the aberrant expression of SLC22A17 in cancer have been described, nor the epigenetic alterations associated with SLC22A17 dysregulation in cancer." (PMID 39358721, 2024). "However, the precise epigenetic mechanisms underlying the gene regulation of Lipocalin 2 (LCN2), SLC22A17, and MMP9 in cancer still remain unclear." (PMID 36211450, 2022). "The results of this study suggested that LCN2, SLC22A17, and MMP9 genes interact with each other, indicating their synergic involvement in cancer." (PMID 36211450, 2022). "Subsequently, correlation analysis between the expression of LCN2, SLC22A17, and MMP9 genes and RPPA protein levels was performed to identify their involvement in cellular processes and cancer pathways." (PMID 36211450, 2022). "Cancer cells of BC‐LM and LC‐LM make use of iron collection system LCN2/SLC22A17 to outcompete the macrophages, the major iron‐utilising cells, for sparse environmental iron, which promotes cancer cells growth and evades immune responses." (PMID 35678121, 2022). "Of these, LCN2 and solute carrier family 22 member 17 (SLC22A17) were exclusively expressed in cancer cells and not in macrophages." (PMID 41303420, 2025). "Besides ECM degradation, iron metabolism is also critical for cancer cell proliferation and survival, whose trafficking is regulated by the NGAL receptor (NGALR), better known as Solute Carrier Family 22 Member 17 (SLC22A17)." (PMID 39358721, 2024). "Although the epigenetic regulation of NGAL and MMP-9 in cancer was widely investigated, no data on the role of methDNA in the regulation of SLC22A17 in CM are reported in the literature." (PMID 39358721, 2024). "Furthermore, gene ontology analysis (STRING) was performed for each protein cluster to assess the matching of proteins with the KEGG pathways to identify the role of LCN2, SLC22A17, and MMP9 genes in cellular processes and cancer pathways." (PMID 36211450, 2022).
cancer (continued). "SLC22A17 and APOD were found to be dysregulated in diverse cancers." (PMID 34306002, 2021). "A prognostic model constructed with SLC22A17 and APOD might have vital roles across multiple types of cancers." (PMID 34306002, 2021). "However, the DNA methylation regulation of LCN2 and SLC22A17 has not been sufficiently investigated in cancer." (PMID 36211450, 2022).
bacterial infection (4 papers, 2016 to 2024). "SLC22A17 is a cell surface receptor for Lipocalin 2, an antibacterial protein that acts by sequestering iron during bacterial infection and has recently been reported to be involved in various pathophysiological conditions in various organs and tissues, including the heart and brain." (PMID 38969939, 2024).
infection (3 papers, 2020 to 2024). The state of being infected such as from the introduction of a foreign agent such as serum, vaccine, antigenic substance or organism. "We further combined the genetic manipulation of Slc22a17 with GCaMP6s infection to track the in vivo neural activity of the mPFC when the mouse faced stress on the elevated plus-maze." (PMID 38589429, 2024).
Digestive system tumor (2 papers, 2020 to 2022). "In particular, the gastrointestinal tumors (ESCA, STAD, READ, and COAD) showed both the highest expression of LCN2 and the lowest expression of SLC22A17 compared to the related normal tissues." (PMID 36211450, 2022). "Digestive system tumor compared with paracancer, there was a significant difference (P < 0.05) in the expression of SUPV3L1 and SLC22A17." (PMID 32164594, 2020).
SLC22A17 also shares sentences with these, for which no sentence is quoted: Cerebral ischemia (2 papers); esophageal squamous cell carcinoma (2); hepatocellular carcinoma (2); acquired Fanconi syndrome (1); acute lymphoblastic leukemia (1); alcohol hepatitis (1); bacterial sepsis (1); brain tumor (1); cervical cancer (1); Chronic Lymphocytic Leukemia (1); chronic myeloid leukemias (1); cognitive decline (1); Cushing syndrome (1); cyst (1); dilated cardiomyopathy (1); epithelial carcinomas (1); glomerulonephritis (1); heart failure (1); hemochromatosis (1); ischemic stroke (1); leukemia (1); lung adenocarcinoma (1); malaria (1); multiple myeloma (1); myeloproliferative neoplasm (1); neuronal tumor (1); nonalcoholic steatohepatitis (1); Obesity (1); Pain (1); pancreatic ductal adenocarcinoma (1).
A further 6 diseases each share a sentence with SLC22A17 in 1 paper.